CRP (C-reactive protein)
Diseases named in the same sentence as CRP in open-access papers (continued):
Sharing a sentence is not in itself a finding about the gene and the disease.
COVID-19 (continued). "Although using CRP in a continuous manner may offer an improved understanding of the contribution of CRP within each analysis, it does not allow CRP to be used by clinical teams to guide management of patients with COVID-19." (PMID 33683344, 2021). "C-Reactive Protein plasma levels were found to be higher in MIS-C rather than in COVID-19 children." (PMID 34778310, 2021). "CRP are normally lacking in viral infections, while adaptive immunity appears to be essential for COVID-19 virus clearance, and the macrophage activation syndrome may explain the high serum CRP contents and contribute to the disease progression." (PMID 34447386, 2021). "As CRP is consistently elevated, this biomarker might not have predictive value for bacterial infections in the initial phase of COVID-19." (PMID 34021897, 2021). "Notably, pregnant patients with COVID-19 had significantly higher levels of C-reactive protein (CRP) compared to the non-pregnant Covid-19 patients and healthy pregnant patients, reflecting an enhanced immune vigilance against infection during pregnancy." (PMID 34012458, 2021). "We next compared cardiac injury markers in hypertensive-COVID-19 patients with and without CRP/hsCRP incensement and found that patients who presented an elevated inflammatory status also demonstrated a significant increase in LDH and a moderate increase in CK (p = 0.07) and CK-MB (p = 0.09)." (PMID 34789776, 2021). "Furthermore, we found significantly higher levels of C-reactive protein in all of our COVID-19 diabetic patients than non-diabetic COVID-19 patients." (PMID 33842709, 2021). "A study conducted on patients with severe COVID-19 has shown that in all CP-transfused patients who obtained SARS-CoV-2 serum, an increase in oxygen saturation and lymphocyte counts and an improvement in their liver function and C-reactive protein (CRP) were observed." (PMID 33498679, 2021). "The neural network with two hidden layers (the first layer has 128 neurons and the second layer has eight neurons) also illustrated that RF model based on the combination of lymphocyte (%), neutrophil, LDH, CRP, and α-HBDH could best predict the outcome of COVID-19 patients." (PMID 34541519, 2021). "In addition, CRP levels in COVID-19 patients with depression are higher than those without depression." (PMID 35059135, 2021). "Similarly, it was reported that a prompt decrease in CRP and IL-6 was found in responders of severely ill patients with COVID-19 to tocilizumab but not in non-responders." (PMID 34631752, 2021). "It is noteworthy that severe COVID-19 infection, which almost always is accompanied by the acute respiratory distress syndrome, is very distinguishable from mild infection of COVID-19 in terms of cytokine, C-reactive protein and ferritin levels, as well as in the lack of eosinopenia in mild cases." (PMID 34680972, 2021). "The current study revealed significantly higher CRP levels in severe cases than in nonsevere patients suggesting that the CRP level may be a biomarker of disease severity and progression in patients with COVID-19." (PMID 33968148, 2021). "Our findings suggest that TYMP is a more sensitive and specific marker for COVID-19 because in the COVID-19 patients with the lowest CRP (<20 mg/L), their TYMP expression was significantly higher than the non-COVID-19 patients, even they have a very high level of plasma CRP (>60–180 mg/L)." (PMID 33829029, 2021). "Baseline levels of ferritin, CRP and procalcitonin have been related to mortality or poor outcomes in hospitalized COVID-19 patients but not in our final regression model, in agreement with other COVID-19 –TCZ cohorts." (PMID 34276355, 2021). "LDH, CRP, and α-HBDH were also positively correlated with respiratory rate and severity classification (p < 0.05) in patients (896 were in general, 392 were in severe, and 63 were in critical), illustrating the importance of these phenotypic characteristics on outcome in COVID-19 patients." (PMID 34541519, 2021).
COVID-19 (continued). "Similarly to SARS, inflammation plays an important role in the pathophysiology of COVID-19, and patients with severe disease may have high serum concentrations of inflammatory markers such as IL-6, TNF, C-reactive protein (CRP), and D-dimer." (PMID 34960790, 2021). "The clinical, biological, radiological characteristics including time from first symptoms and admission to DE-CTPA, oxygen requirements, CRP, D-dimer levels, duration of hospital admission and death were compared within the COVID-19 group between patients with (PD +) or without PD (PD-)." (PMID 33595746, 2021). "Therefore, we believe that CRP has a certain suggestive role, but it is not significantly related to the severity and death of diabetic patients infected with COVID-19." (PMID 34164413, 2021). "In one study, COVID-19 patients with an admission CRP ≥65.1 mg/l were more likely to require high-flow oxygen, noninvasive or invasive mechanical ventilation, continuous renal replacement therapy or extracorporeal membrane oxygenation (OR: 8.9; 95% CI 1.0–74.2)." (PMID 34567235, 2021). "The severity of COVID-19 at admission and serum CRP level at admission were not higher in the FDG." (PMID 34772350, 2021). "In a recent study of 655 COVID-19 patients presented to the Emergency Department at a University Hospital of which 15% were hospitalized, 42% of hospitalized patients had elevated AST levels and higher serum CRP, lactate dehydrogenase (LDH), ferritin and IL-6 levels." (PMID 34287285, 2021). "Lagunas-Rangel, in his study on the assessment of changes in the neutrophil-to-lymphocyte ratio (NLR) and lymphocyte to C-reactive protein ratio (LCR) in patients with severe coronavirus disease 2019 (COVID-19), showed that NLR is higher in infected patients than in noninfected patients." (PMID 34372587, 2021). "We investigated serum D-dimers, CRP, ferritin, cardiac troponin I, IL-6 levels during the acute phase of infection (SARS-CoV-2 RNA positive) and were monitored longitudinally in hospitalized patients with moderate to severe COVID-19 and in mild ambulatory COVID-19 patients in home quarantine." (PMID 34262116, 2021). "Furthermore, prognostic biochemical markers in COVID-19 including the inflammatory cytokines C-reactive protein (CRP), interleukin-6, and interleukin-10, were not measured due to limited resources." (PMID 33781275, 2021). "Additionally, high-sensitivity C-reactive protein–albumin ratio (HsCAR) and low prognostic nutritional index (PNI) and the ratio of interleukin (IL)-6 to IL-10 were reported to be related to the prognosis of COVID-19 patients." (PMID 34217339, 2021). "Similar to our study, a retrospective study delineating the clinical characteristics of 113 non-survivors with COVID-19 showed that the CRP was significantly elevated in deaths compared with recovered patients with severe diseases [113 (69.1–168.4) vs. 26.2 (8.7–55.8)]." (PMID 34733858, 2021). "Therefore, COVID-19 patients with CHD were four times more likely to die than average COVID-19 patients, with an elevated level of proinflammatory cytokines such as IL-6, CRP, and procoagulant factors such as D-Dimer20." (PMID 34903765, 2021). "Several reports of non-MHD patients with COVID-19 have described elevated levels of neutrophils and CRP with lymphopenia, but very few reports have considered the cost-effective markers NLR, PLR, MLR, and LCR to aid complication predictions and response to the therapeutic measures performed." (PMID 33747583, 2021). "Increased CRP values reportedly are characteristic in COVID-19 but not in other viral infections." (PMID 34510338, 2021). "Similarly, higher levels and a higher velocity of increase of CRP levels were observed in non-survivors compared to survivors among 577 middle-aged adults hospitalized for COVID-19." (PMID 34506514, 2021).
COVID-19 (continued). "However, early detection of high level of serum CRP, ALT/AST and ALP combined with a clinical COVID-19 symptom and CT scan findings may be used as an index for the presence and severity of the disease." (PMID 34158795, 2021). "Third, the study was based on the hospitalization of patients with severe COVID-19 rather than on the onset of symptoms to discharge, which may lack earlier data on CRP and Alb levels." (PMID 34900028, 2021). "Unlike Covichem, a severity score applied to COVID-19 identified CRP as a good predictor." (PMID 33956870, 2021). "Unlike other markers of inflammation, CRP is routinely measured in patients with COVID-19." (PMID 33256890, 2021). "Similarly, the highest CRP was more frequently seen in patients with COVID-19 rather than in those with influenza in a Finnish study." (PMID 34859002, 2021). "Common inflammatory markers seen in endothelial dysfunction including C-reactive protein (CRP), IL-6, interferon gamma-induced protein-10 (IP-10), monocyte chemoattractant protein-1 (MCP-1), macrophage inflammatory protein-1 alpha (M1P1A), and TNF-α were also elevated in patients with COVID-19." (PMID 34012410, 2021). "CRP is normally lacking in viral infections, while adaptive immunity appears to be essential for COVID-19 virus clearance, and the macrophage activation syndrome may explain the elevated serum CRP contents." (PMID 34447386, 2021). "This may explain the simultaneous attenuation of CRP and inflammatory cytokines (CD4( +) IFN-γ) in hemodialysis patients after calcitriol treatment, or elevation of both CRP and cytokines in severe COVID-19 patients." (PMID 32876941, 2020). "However, the inverse relationship between CRP on admission and frailty has not previously been noted in COVID-19." (PMID 32734464, 2020). "Severe COVID-19 cases had significantly higher blood level of procalcitonin (SMD = 0.72, 95%CI: 0.34;1,11; P-value: < 0.001; n = 1509), interleukin-6 (SMD = 0.93, 95%CI: 0.25;1.61; P-value: 0.007; n = 875),and C-reactive protein (SMD = 1.34, 95%CI:0.83;1.86; P-value: < 0.001; n = 1974)." (PMID 32879731, 2020). "However, LDH, CRP, and IL-6 values were not significantly different between COVID-19 ARDS patients and patients with non-COVID-19-associated pneumonia (each p > 0.05)." (PMID 33123171, 2020). "This patient, admitted with altered blood parameters (CRP 6.8 mg/dL; ferritin 1774.0 ng/mL) and abnormal lung CT scan (25–50% ground-glass opacities extension), evolved to a severe COVID-19 phenotype, but not requiring ICU monitorization or mechanical ventilation." (PMID 33270751, 2020). "Laboratory findings of Corona Virus Disease 19 (COVID-19) include lymphopenia with depletion of CD4 and CD8 lymphocytes, prolonged prothrombin time, elevated lactate dehydrogenase (LDH), D-Dimer, alanine transaminase, C-reactive protein (CRP), and creatinine kinase." (PMID 32973526, 2020). "In our study, the four predictors (age, NLR, D-dimer and CRP) obtained on admission were selected by the LASSO analysis to construct a predictive nomogram, which exhibited good discrimination and calibration in the individualized prediction for the death probability of COVID-19 patients." (PMID 32867787, 2020). "For COVID-19, dynamic changes in hematologic and immunologic markers, such as progressive decline in eosinophils, lymphocytes, and platelets and dynamic increases in NEUs, IL-6, PCT, D-dimer, and CRP, during hospitalization are indeed strong suggestions for progression of the disease." (PMID 33157938, 2020). "The Chinese national guidelines for the diagnosis and treatment of COVID-19 state that it is common for patients to have a normal or decreased WBC count, a and decreased neutrophil count; that some patients have increased LDH, and myoglobin; and that most patients have an elevated CRP." (PMID 32502054, 2020).
COVID-19 (continued). "Moreover, the levels of C-reactive protein (CRP), which is a peripheral inflammatory indicator, positively correlated with the PHQ-9 total score (R = .37, p = 0.003, Spearman's correlation) of COVID-19 patients with symptoms of depression." (PMID 33093946, 2020). "Based on current clinical evidence, inflammatory biomarkers such as C-reactive protein (CRP), serum ferritin, procalcitonin, interleukins, and the erythrocyte sedimentation rate (ESR), play key roles as predictors in evaluating severity and mortality in COVID-19 patients." (PMID 33062473, 2020). "Additionally, it is well established that CRP is elevated in patients with COVID-19 and is higher in patients with the severe disease than nonsevere." (PMID 33291617, 2020). "Taking into account that a timely administration of EGCG to COVID-19 patients is most likely crucial, we suggest administering EGCG, orally, at the dosage of 600–900 mg/die, once the symptoms aggravate and/or the blood C-reactive protein, or other markers of inflammation, increase." (PMID 32708322, 2020). "The COVID-19 patients with lung fibrosis were older and had higher plasma levels of CRP and prevalence of hypertension compared with those without fibrosis (p < 0.001 for CRP; p = 0.008 for the prevalence of hypertension)." (PMID 33133104, 2020). "In the late stage of COVID-19, severe cases had extremely low CD4+ T cells and CD8+ T cells, but unusually high neutrophils [6.5 × 109/L (IQR, 4.8–9.6)], procalcitonin [0.27 ng/mL (IQR, 0.14–1.94)], C-reactive protein [66 mg/L (IQR, 25–114)] and an extremely high level of interleukin-6." (PMID 32983157, 2020). "Serum inflammatory factor levels of IL-2, IL-1β, IL-5, IL-4, IL-6, IL-8, IL-10, IL-17, IL-12P70, IFN-α, TNF-α, IFN-γ, endotoxin, CRP, and hs-CRP of non-severe COVID-19 patients across different age groups (< 50, 50–60, 60–70, and ≥ 70 years) were not significantly different." (PMID 33065551, 2020). "Moreover, the dynamic changes of neutrophils and CRP were also presented, and compared with COVID-19 patients without cancer, cancer patients with COVID-19 showed higher neutrophil counts and CRP levels." (PMID 33192519, 2020). "The results of our study should also warn that when dealing with the suspicion of a positive COVID-19 in a patient admitted to the emergency room a few days after the onset of symptoms and without severe alterations of CRP and LDH, physicians should not be surprised to be faced with a negative CXR." (PMID 32894449, 2020). "According to the present study, physicians in countries with limited testing resources may need to include blood markers (lymphocytes, neutrophils, CRP and ESR) to prioritize the patients with a high suspicion of having COVID-19 for rRT-PCR test based on these markers." (PMID 33738019, 2020). "Moreover, compared with COVID-19 patients without cancer, cancer patients with COVID-19 have higher neutrophil counts and CRP levels." (PMID 33192519, 2020). "Age, aspartate aminotransferase, alanine aminotransferase, fibrinogen, sedimentation, C - reactive protein, and ferritin levels were significantly higher and lymphocyte levels were significantly lower in COVID-19 patients with lung involvement compared with those without lung involvement." (PMID 32979900, 2020). "For example, one study indicated that CRP and LDH might be good predictors of COVID-19 severity." (PMID 33251228, 2020). "Taken together, consistent with previous research 2,5, the ESR, CRP, PT, IL6, lymphocyte count, GGT, Prealbumin and CD4 have important value in the diagnosis of COVID-19, and the decrease of GGT may be an important indicator for judging the intestinal dysfunction of patients." (PMID 32547309, 2020). "Laboratory investigations among COVID-19 patients did not reveal specific characteristics—lymphopenia and elevated inflammatory markers such as CRP are some of the most common haematological and biochemical abnormalities, which had also been noticed in SARS121." (PMID 33188232, 2020).
COVID-19 (continued). "Finally, the mean of each inflammatory marker was in range among COVID-19 patients except lactate dehydrogenase (LDH) (479 vs. U/L), troponin I (210.76 vs. 0.0–34.0 ng/L), C reactive protein (CRP) (150.43 vs. 0.0–5.0 mg/L) and procalcitonin (1.02 vs. 0.0–0.05 ng/mL), which were all higher." (PMID 32722020, 2020). "Severe COVID-19 patients show a notable elevation of inflammatory cytokines such as IL-2R, IL-6, granulocyte colony-stimulating factor (GCSF), macrophage chemotactic protein-1 (MCP1), macrophage inflammatory protein (MIP)1A, TNF-α and anti-inflammatory compounds such as CRP." (PMID 32876941, 2020). "In the present study, the significant correlation between CRP and RDW levels, especially before the outcome, reinforces the hypothesis that severe inflammation is related to hematological changes, so indicating a potentially worse prognosis in COVID-19 patients." (PMID 40362375, 2025). "Research has demonstrated that, compared to COVID-19 patients without diabetes, those with diabetes exhibit a higher incidence of lymphopenia (44.5% vs. 32.6%) and elevated levels of inflammatory markers (C-reactive protein: 57.0% vs. 42.4%, procalcitonin: 33.3% vs. 20.3%)." (PMID 40861049, 2025). "In the post-COVID-19 period (n = 109), children in the antibiotic group were significantly older (p < 0.001) and had higher neutrophil counts (p < 0.001) compared with the non-antibiotic group, whereas the frequencies of fever and CRP levels were comparable between the two groups." (PMID 41153485, 2025). "This pattern parallels broader COVID-19 cohorts in which early elevations of CRP, D-dimer, and leukocyte ratios have been identified as independent predictors of severe disease and mortality, and where admission ferritin and CRP levels strongly differentiate survivors from non-survivors." (PMID 41463074, 2025). "CRP, a nonspecific but reliable marker of inflammation, was elevated by an average of nearly 20 mg/L in co-infected patients (87.4 vs. 68.9 mg/L, p < 0.001), while IL-6, a critical cytokine in COVID-19 pathophysiology, was also notably higher (62.1 vs. 48.7 pg/mL, p < 0.001)." (PMID 39857695, 2025). "Although CRP is a non-specific biomarker of acute infections and elevates across diverse conditions, especially in bacterial infections, our results are consistent with previous studies to support it as a reliable biomarker to distinguish adults and children with COVID-19." (PMID 39967737, 2025). "COVID-19 patients with severe disease exhibit increased monocyte counts with higher frequencies of classical monocytes, lower frequencies of intermediate/non-classical monocytes and elevated plasma levels of C-reactive protein (CRP) and serum TF in comparison to mild disease." (PMID 38555403, 2024). "Furthermore, both the prognostic value with regard to 30-day all-cause mortality of CRP (AUC = 0.467; 95% CI 0.311—0.402; p = 0.311) and PCT (AUC = 0.455; 95% CI 0.382–0.528; p = 0.221) was poor and comparable to the AUCs including COVID-19 patients (p > 0.05) (data not shown)." (PMID 37204560, 2024). "However, other known factors with a prognostic role for severe COVID-19 evolution, such as respiratory dysfunction, radiological lesion extent, neutrophil/lymphocyte ratio, and elevated CRP values, did not significantly influence the post-COVID-19 evolution of OSA." (PMID 39202792, 2024). "However, a decrease in C-reactive protein levels should not be used as a sole variable to identify COVID-19 patients suitable for weaning; as in our study, the area under the ROC curve demonstrated poor accuracy in discriminating extubation outcomes, with low sensitivity and specificity." (PMID 38597482, 2024). "Therefore, it is important to understand whether the use of tocilizumab can improve the inflammatory response in severe cases of COVID-19 or not, and if these changes can be followed by quick and inexpensive tests such as CRP measurement." (PMID 38687065, 2024).